LY6G6F-LY6G6D (LY6G6F-LY6G6D readthrough)
Synonyms: MEGT1; MEGT-1; G6F-LY6G6D
Gene: Protein-coding gene on chromosome 6 (31,706,904 to 31,717,918, forward strand). Ensembl gene ENSG00000250641.
Genetic constraint (gnomAD): Loss-of-function variants: 27 observed, 34.93 expected, observed/expected ratio (o/e) 0.77, 90% interval 0.57 to 1.07. The upper end of that interval is the gene's LOEUF score, 1.07, which puts it in group 4 of 6, group 1 being the genes least tolerant of losing a copy. Missense variants: 325 observed, 408.77 expected, observed/expected ratio (o/e) 0.8, 90% interval 0.73 to 0.87. Synonymous variants: 137 observed, 163.05 expected, observed/expected ratio (o/e) 0.84, 90% interval 0.73 to 0.97.